IL2 (interleukin 2)
Diseases named in the same sentence as IL2 in open-access papers (continued):
Sharing a sentence is not in itself a finding about the gene and the disease.
tumor (continued). "They managed to demonstrate effective cytotoxicity against tumour cells by significantly generating IL-2, IFN-γ, GM-CSF, and TNF-a with respect to non-engineered T cells." (PMID 39596267, 2024). "Co-culture of Bregs with tumour-infiltrating follicular cytotoxic CD8+ T (Tfc) cells increased Tfc expression of IL-10 and reduced Tfc expression of pro-inflammatory IFN‐γ, TNF, and IL-2 in NSCLC patients." (PMID 39346706, 2024). "Among the tumour-reactive clonotypes, those that expanded ex vivo exhibited higher IL-2 signalling signature scores in baseline tumours compared with clonotypes that did not expand." (PMID 38658764, 2024). "However, in patient 01002 and 01003 we observed high peak values of IL-2 and IFN-γ, the cytokines play important roles in anti-tumor T cell responses in TME." (PMID 38642109, 2024). "Furthermore, in order to determine the expression levels of Decorin, IL-2, and IFN-γ in tumor tissue, a qPCR assay was conducted." (PMID 39482550, 2024). "This is consistent with the previous finding that bryostatin-1 blocks the IL-2 secretion in activated T cells from tumor-draining lymph nodes." (PMID 39877358, 2024). "Notably, in the presence of exogenous IL‐2, CD19‐CAR‐DNTs exhibit more robust recursive killing potential at high tumor cell loads, achieving durable TGI." (PMID 39720695, 2024). "The DMPtNPS@cGAMP + RT group exhibited a significant increase in anti‐tumor cytokines, namely IFN‐γ, IFN‐α, IFN‐β, TNF‐α, and IL‐2, and a more pronounced decrease in pro‐tumor cytokines, including IL‐1β, IL‐10, IL‐4, and TGF‐β, as measured by ELISA kits, in comparison to the other treatment groups." (PMID 38063844, 2024). "IL-2 was detectable only in presence, but not in absence, of tumor cells, while TNFα was unchanged and all other cytokines (IL-6, IFN-γ, GM-CSF, IL-10) were slightly reduced without tumor cells." (PMID 38514793, 2024). "Ongoing studies are investigating the modulation of IL-2 dosage to minimize toxicities without compromising the anti-tumor effect." (PMID 38785789, 2024). "Tcms are phenotypically similar to Tn cells in that they rapidly produce IL‐2 in response to TCR activation, leading to the differentiation and generation of many Teffs that migrate to tumour sites, as well as increased phagocytosis and clonal proliferation rates." (PMID 38468489, 2024). "However, when we analyzed IL2 production by CD8+ T cells and CD4+ Tconv cells, we found that FS120m induced marginally increased expression among cells from the spleen and tumor-draining lymph nodes." (PMID 38995700, 2024). "We observed a negative correlation between GM-CSF and tumour growth (R2 = 0.2864, p = 0.0486) and a non-significant trend for IL-2 (R2 = 0.2288, p = 0.0713)." (PMID 38745230, 2024). "IFN-γ, TNF and IL-2 were found to be considerably increased by PPL-C when we assessed the cytokine concentration in cell culture supernatants, which further demonstrated that lymphocytes in immunotherapy-treated mice have been reactivated by tumor cells." (PMID 38745661, 2024). "While combining IL-2 with chemotherapy and/or interferon boosts tumor response rates, it does not lead to better long-term survival outcomes." (PMID 39449907, 2024). "In melanoma models, T cells harboring the CARD11-PIK3R3 fusion gene showcased enhanced tumor infiltration capabilities, accompanied by the accumulation of highly functional stem cell-like T cells, culminating in heightened production of TNF, IFNγ, and IL-2." (PMID 38730483, 2024). "These pathways include tumor necrosis factor alpha (TNFα) signaling, inflammatory response, IL2 and signal transducer and activator of transcription 5 (STAT5) signaling, and interferon-gamma (IFNγ) response, suggesting its involvement in anti-tumor immune response." (PMID 38515213, 2024).
tumor (continued). "Subclustering and GSEA in non-malignant cell clusters revealed similar tumor-wide changes in transcriptional phenotype, with increased IFNα, IFNγ, inflammatory response and IL2-Stat5 signaling again observed as well as decreases in oxidative phosphorylation." (PMID 38286828, 2024). "Research has demonstrated that the combination of γδ T cells, IL-2, and [(HER2) 2Vγ-9] was employed in the treatment of tumor-bearing models established using the pancreatic cancer cell line PancTu-I and SCID Beige mice, resulting in significant inhibition of tumors in all mice." (PMID 39253082, 2024). "The signaling pathways regulated by activating T cell nuclear factor (NFAT) and activating protein (AP) inhibit the proliferation of CD + 8 T cells and CD + 4 T cells, and reduce the levels of interleukin-2 (IL-2) and interferon- γ (IFN)- γ) the tumor’s secretion leads to tumor immune escape." (PMID 38581529, 2024). "In addition, CTLA4 pathway can also significantly enhance the secretion of IL-2 by CD4+T cells and promote the proliferation, survival and tumor killer activity of T, NK and other immune cells in the tumor microenvironment." (PMID 38713378, 2024). "One would expect that tumor‐targeted ICK would be less toxic and exhibit higher efficacy, but surprisingly, IL‐2‐Fc had less toxicity and equivalent antitumor efficacy compared to M5A‐IL‐2 ICK." (PMID 38317590, 2024). "Blood and tumor tissue-based flow cytometric phenotyping reveals an increase in effector memory CD8 and CD4 T cells and a decrease in immunosuppressive cells accompanied by a significant increase in IL-2, IFN-γ, and GM-CSF levels in the combination group." (PMID 39218928, 2024). "When anti-MSLN CAR-T cells combined with OAd-TNFa-IL2 (an oncolytic adenovirus expressing TNF-α and IL-2) were applied to human PDA xenotransplantation mice, the activity, proliferation, tumor invasion and killing ability of the resulting anti-MSLN CAR-T cells were enhanced." (PMID 39023820, 2024). "We observed that PDAC patients with higher IL-2 mRNA levels exhibited improved overall survival and increased infiltration of CD8 + T cells, NK cells, naïve B cells, and resting myeloid DCs in the tumor microenvironment." (PMID 38554155, 2024). "In AML-exposed CAR T cells, C-JUN did promote IL-2 expression at the RNA and protein levels, whereas IFN-γ was only upregulated at the protein level, suggesting that C-JUN may promote anti-tumor efficacy at least partly by increasing these cytokines." (PMID 39039086, 2024). "Intriguingly, CAR T cells harboring CARD11-PIK3R3 exhibited robust target cell elimination, irrespective of IL-2 levels, underscoring their potent anti-tumor activity." (PMID 38730483, 2024). "The expression of activation-specific genes (IFNG, GZMB, and TNFRSF9) and cell proliferation-specific genes (IL2, IL2RA, and CD28) decreased with the increasing rounds of tumor stimulation, especially from round 2 (the round in which tumor-killing ability begins to decline)." (PMID 39657666, 2024). "We observed specific release of IFNg, GranzymeB and Perforin upon anti-CD3 + IL2 treatment and not upon LPS treatment for the same tumor sample." (PMID 38383563, 2024). "In mouse models, STK-012 showed improved anti-tumor efficacy over WT IL-2 or a non-α IL-2 and did not induce CLS." (PMID 39114660, 2024). "Moreover, the production of cytokines such as IL-2, IL-4, IL-6, IL-7, IFN-γ, IFN-α, TNF-α, CCL7, and CCL28 can stimulate an anti-tumor response." (PMID 38533507, 2024). "In order to evaluate the effect of mIL15 on the production of anti-tumor cytokines, we co-incubated UN-TIL+IL2, TIL-mIL15+IL2, and TIL-mIL15-IL2 cells with anti-CD2/CD3/CD8-conjugated T cell activation magnetic beads and measured the levels of IFN-γ and GZMB in the cell culture supernatant." (PMID 39650651, 2024). "It is noteworthy that IL2 and IL12 are pivotal inflammatory cytokines intrinsic to tumor immunity." (PMID 38881859, 2024).
tumor (continued). "Specifically, compared with DMSO treatment, UA treatment increased the expression of IFN‐γ, TNF‐α, IL‐2, CD107a, and granzyme B in OT‐I CD8+ CTLs and enhanced the cytotoxic activity against antigen‐pulsed EL4 tumor cells in vitro." (PMID 38447147, 2024). "Results of in vitro killing assay indicated that all the four groups of T cells could repress the tumor cell growth in vitro, especially the T cells vaccinated by DCs that co-cultured with PBMC and IL-2." (PMID 38554155, 2024). "Furthermore, we analyzed the correlation between LINC00665 levels in metastatic lung cancer patients and immune-suppressive cytokines (TGF-β, IL-10, and IL-1β) as well as anti-tumor cytokines (IFN-γ, IL-2, and TNF-α)." (PMID 38951802, 2024). "Although cytokine production, such as IL-2 and IFN- γ, is a classical model for the function of CD4+ T cells in tumor immunity, the CD40L–CD40 axis that activates DCs through CD4+ T cells and the CD70–CD27 axis that activates CTLs through activated DCs constitute a new concept for helper function." (PMID 37881436, 2023). "We demonstrate here in mice that a triple combination of a CD122-directed IL-2 derivative, RT, and anti-PD1 may act as a rather potent personalized in situ vaccine and tremendously increase the number of tumor-specific CD8+ T cells in the blood circulation." (PMID 37045833, 2023). "rNDV-human IL-2 along with TRAIL triggered T cell activity and upregulated the expression of apoptotic genes (caspase-8, caspase-9, caspase-3, FasL, and BAX) in melanoma and HCC tumor cell mice models via TRAIL." (PMID 37629483, 2023). "Moreover, it has been shown that levels of serum TNF-α, IL-2, and serum CD44 (sCD44) are all increased in NHL and correlate with tumor burden, the presence of symptoms, and other clinical and laboratory variables." (PMID 36831345, 2023). "A high dose of IL-2 leads to severe side effects, whereas low-dose IL-2 enhances expansion ability but has no influence on anti-tumor capacity." (PMID 37144558, 2023). "Mice treated with IL2-F8-TNFmut showed significant tumor growth retardation compared with the mice treated with saline or with the negative control molecule IL2-KSF-TNFmut." (PMID 37092450, 2023). "As previously discussed, IL-2 acts to increase tumor immunogenicity but is not well tolerated when delivered systemically at efficacious doses." (PMID 36900196, 2023). "In addition, SFI reduced the levels of proinflammatory cytokines IL-2, IFN-γ, and TNF-α in spleen, However, the mRNA levels of IL-2, IFN-γ and TNF-α in tumor tissues were significantly increased, while IL-6 mRNA levels were significantly decreased." (PMID 37355637, 2023). "In conclusion, the current study provided evidence that CPT treatment could potentially enhance the anti-tumour immune response in HCC patients through increasing the plasma levels of CD4, CD8, IL-2, IL-12, and IFN-γ after CPT administration." (PMID 37704828, 2023). "Patients who had no anti-tumor response to high-dose IL-2 had significantly greater expansion of Treg cells compared to patients with objective anti-tumor responses, suggesting an association of the inhibitory role of these cells with poor clinical response." (PMID 37174716, 2023). "Non-specific immunity against tumor is played by neutrophils, macrophages and NK cells which have been activated by IL-2." (PMID 37520880, 2023). "Here, the increase of IL-2, IL-6 were found in the primary gastrointestinal cancer patients without anti-tumor treatments." (PMID 36765353, 2023).
tumor (continued). "Consistent with our hypothesis, the Aspiletreins bound to the targets with high affinity and likely inhibited the tumor-promoting functions of STAT3, VEGFA, HSP90AA1, and FGF2 or enhanced tumor-suppressing activity of IL2, or both." (PMID 36707691, 2023). "CD4+ T cells may also provide local help for CD8+ T cells within tumors by secreting cytokines such as IL-2 and IFN-γ, supporting CD8+ T cell survival and recruitment to the tumor." (PMID 36512410, 2023). "Numerous studies have shown that the MYC-dependent pathway in tumor cells can indirectly affect the expression of cytokines in the TIME, such as the reduction in the expression of interleukin-2 (IL-2), interferon-γ (IFN-γ), and perforin and the increase in the expression of interleukin-6 (IL-6)." (PMID 36966168, 2023). "Our finding that IL-2 restriction is the major mechanism of Treg-mediated regulation of self- and tumor-reactive CD8+ T cells does not exclude the involvement of additional mechanisms regulating other immune cell types, such as conventional CD4+ T cells." (PMID 36705564, 2023). "Bifunctionality of IL-2, a well-known T cell growth and differentiation factor, reveals itself in stimulating Th1 cells and CTL with anti-tumor activity, but at the same time, serving as a potent activator of Tregs, which inhibits immune-mediated anti-tumor activity." (PMID 36677048, 2023). "The secretion of cytokines, such as interleukin-2 (IL-2), tumor necrosis factor alpha (TNF-α), interferon-gamma (IFN-γ), and cytolytic granules, such as granzyme B (GB), are the main functional attributes of CD8+ T cells that exhibit anti-tumor activity." (PMID 36798119, 2023). "Secondly, we quantified release of cytokines (i.e., IFNγ, IL-10, IL-2, IL-6, TNFα, GM-CSF, IL-12p70, IL-1b and IL-8) and granzyme B by using the MSD platform in supernatants collected from the TDCC assay with the tumor cell lines SK-CO-1, MKN-45 and H2122 after 48 h." (PMID 38087365, 2023). "Conversely, other research indicates that IL-2/IL-2R signaling may promote CTL and NK cell infiltration into the TME, enhancing anti-tumor immune responses and impeding tumor growth." (PMID 37516849, 2023). "Tα1 increases the number of tumor-infiltrating CD4+ and CD8+ T cells in melanoma and breast cancer xenograft models due to its role in induction of T cell differentiation, enhancement of IFN-γ and IL-2 production, and downregulation of T cell apoptosis." (PMID 37529610, 2023). "IL-2 can significantly promote the proliferation and activation of T cells, particularly CD8+ cytotoxic T cells, which can directly kill tumor cells." (PMID 38259287, 2023). "A study showed that an anti-CD3 nanobody could successfully activate T cells, raise the secretion of IL-2 and IFN-γ cytokines and suppress tumor growth in a xenograft mouse model." (PMID 36761751, 2023). "Nevertheless, even if unadjusted pool estimations showed a trend toward better ORR outcomes among patients who received either NMA or post-infusional IL2, multivariate model did not demonstrate any higher likelihood of tumor response in these subsets." (PMID 37036865, 2023). "Upon tumor challenge, CAR-T cells exposed to IL-15 exhibited fewer apoptotic features, higher proliferative capacity, and a superior antitumor response than those exposed to IL-2 in vivo." (PMID 38049832, 2023). "The effects of FPC2‐IG‐IL‐2 on tumor‐infiltrating immune cell populations were examined by the immune monitoring of CT26‐bearing mice with intratumorally injected PBS, FPC2‐IG, FPC2‐IG‐IL‐2, and free IL‐2." (PMID 36684086, 2023). "Interestingly, the combination of IL12-MSA and IL2-MSA led to an increased fraction of CD4+ T cells that were Tregs in the TdLN and spleen but a significantly decreased Treg fraction in tumor-bearing lungs." (PMID 37669107, 2023).
tumor (continued). "Besides, impressively decline in Th2 cytokines (interleukin (IL)−10, IL‐6, TGF‐β) and increase in Th1 cytokines (IL‐2, interferon (IFN)‐γ, IL‐12a) were noted in serums from tumor‐bearing mice post Pres and irradiation treatments." (PMID 37875395, 2023). "In fact, preliminary results of a gene expression analysis of fresh tumor tissue provided evidence that the mRNA levels of IL2, IFNG, IL6 and TNFA are increased in SGCT but not in NSGCT, which is in line with our cell culture data (unpublished results)." (PMID 37174085, 2023). "Thus, the phase II clinical study was planned to combine PSMA-specific CAR T-cells with moderate doses of IL-2 supplementation, which were found to be essential for CAR T-cell anti-tumor activities in the TME." (PMID 37020537, 2023). "The multiple effects of IL-2 signaling on the different cell types present in the TME may be beneficial in developing T cells and controlling tumor growth by activating effective antitumor cytotoxic immune responses and killing tumor cells." (PMID 36835413, 2023). "When incubated with tumor cells, EGFR CAR-E27-CCR6 T cells specifically exerted potent cytotoxicity and produced high levels of pro-inflammatory cytokines, including tumor necrosis factor-α (TNF-α), interleukin-2 (IL-2), and interferon-γ (IFN-γ)." (PMID 36982500, 2023). "MDSCs could inhibit T cell proliferation and function by down‐regulating the expression of IL‐2, INF‐γ, and granzyme B.38MDSC also reduces the number of CD8+ T cells and inhibits its cytotoxicity on tumor cells." (PMID 38023716, 2023). "Manipulated TAMs thus gain secretion of various tumor-promoting factors including CCL18, IL-10, and TGF-β while inhibiting the release of cytotoxic factors like IL-2, IL-12, TNF-α, and IFN-γ, impeding the anti-tumor capacity of other immune components and prolong tumor survival." (PMID 38274812, 2023). "Since PTA/IL-2-expanded γδ T cells expressed a high level of NK receptors such as NKG2D and DNAM-1, we examined the cytotoxic activity of γδ T cells against various tumor cell lines." (PMID 37006249, 2023). "In addition, IL-2 signaling also promotes the reprogramming of Tregs into effector T-cells, shifting the TME from a pro-tumor to an anti-tumor state." (PMID 37516849, 2023). "Importantly, this map shows the transition of keywords from older “interleukin 2”, “BCG”, and “TNFα” to the newer “pdl-1”, “tumor microenvironment”, and “immune checkpoint inhibitor”." (PMID 37350946, 2023). "In addition, observably increased Th1 cytokines (IFN‐γ, IL‐12a and IL‐2) and decreased Th2 cytokines (IL‐6, IL‐10 and TGF‐β) in serums were also detected in tumor‐bearing mice post Pres and irradiation treatments." (PMID 37875395, 2023). "The administration of the negative control IL2-KSF-TNFmut did not result in any uptake in the tumor or normal organs." (PMID 37092450, 2023). "Anti-tumor effects mediated by antibody-based TNF-α delivery could also be increased by a proper combination with other cytokines, e.g., IL-2." (PMID 36839658, 2023). "Upon tumor engraftment mice were intraperitoneally injected with a first dose of 1x107 Non-Td or CoStAR-Td TIL, followed by additional 2 injections at 2- and 4- weeks post 1st infusion of 1x107 TIL, with IL-2 provided during the first week after TIL injection." (PMID 38022678, 2023). "We observed that patients with sCRS had significant differences in the initial tumor load, platelets, neutrophil count, lymphocyte percentage, white blood cells, monocyte count, CRP, dosage, IL-2, D-dimer, TAG, red blood cells, hemoglobin, and procalcitonin, as compared with patients without sCRS." (PMID 37854590, 2023). "NK cells are the main cells that mediate the immune response by secreting cytokines such as IFN-α, IFN-γ, IL-2, and GM-CSF, and kill tumour cells non-specifically." (PMID 37767473, 2023).